IDH1 (isocitrate dehydrogenase (NADP(+)) 1)
Diseases named in the same sentence as IDH1 in open-access papers (continued):
Sharing a sentence is not in itself a finding about the gene and the disease.
glioma (continued). "Overall, our findings provide conceptual advances in understanding the role of small GTPases in IDH1-mutated glioma formation." (PMID 32224866, 2020). "IDH1 mutations occur at much higher incidences than IDH2 mutations in lower grade glioma (WHO grade II and III gliomas, LGG)." (PMID 32280672, 2020). "Soon after the discovery, the IDH1/2 mutations are associated with a relatively prolonged patient survival for glioma and glioblastoma in clinics, and has been a rationale for drug target." (PMID 33282092, 2020). "This is the first study to demonstrate a significant correlation between FLT uptake values and IDH1 mutation status in newly diagnosed gliomas." (PMID 32382870, 2020). "Our panel of cell lines deliberately represented a heterogeneous collection of different glioma subtypes, including both IDH1-wildtype and IDH1-mutated cells lines as well as one line that exhibits high-level EGFR amplification and expresses EGFRvIII." (PMID 32178271, 2020). "The purpose of our study is to evaluate the diagnostic potential of non-invasive quantitative T2 mapping in the detection of IDH1/2 mutation status in grade II-III gliomas." (PMID 31914945, 2020). "It was reported high grade gliomas with IDH1 mutations had a longer survival period compared to those with IDH1 wild type." (PMID 32582544, 2020). "The one that prevails over the histopathological classification is the identification of mutations in isocytrate dehydrogenase 1/2 (IDH1/2), which defines gliomas with a better prognosis independently of their tumor grade." (PMID 32570988, 2020). "The autophagy signature-based IDH1 mutation and grade nomogram refined glioma classification for a more individualized and clinically applicable survival estimation and inspired potential autophagy-related therapies." (PMID 32964017, 2020). "IDH1 mutations were also shown to be significantly associated with histological subtypes of glioma (p<0.001)." (PMID 32856857, 2020). "Exact understanding of telomere biology in glioma is therefore of high translational importance, given the completely diverse prognostic impact of TERTp mutations according to the IDH1 mutation status." (PMID 31960234, 2020). "In one report, IDH1 mutations were identified in 5% of pediatric gliomas which collectively had a median age of 16." (PMID 32164789, 2020). "In this report, the neopeptides carrying IDH1 R132H p123-142 mutated region were produced to interact with transgenic human MHC-II molecules in glioma mouse model." (PMID 33228738, 2020). "As much as 30.8% of grades II and III glioma harbor IDH1 mutation compared to 13% in the grades I and IV glioma group." (PMID 32856857, 2020). "Transcriptomic analysis showed that several cell movement-related genes were significantly up-regulated in IDH1-mutated glioma cells." (PMID 32224866, 2020). "A high frequency of mutations in IDH1 and Chr1p19q was detected in gliomas with low PIEZO1 expression, while mutations in TTN, PTEN and NF1 were significantly enriched in cases with high expression of PIEZO1." (PMID 32999349, 2020). "Isocitrate dehydrogenase 1 (IDH1) mutations are genetic alterations that are considered driver mutations and occur in 70–90% of lower-grade gliomas (LGG); however, faithful models that recapitulate this disease are sparse." (PMID 32575619, 2020). "This is consistent with previous studies showing that IDH1 mutation is an independent favorable prognostic marker in glioma." (PMID 32986017, 2020). "We found that the mRNAsi of glioma patients was significantly associated with pathological grade, IDH1 mutation and their OS." (PMID 32725165, 2020). "The rapidity and accuracy of the method in detecting gene mutations in IDH1 can affect the prognosis, intervention, and survival rate in glioma patients." (PMID 33247679, 2020).
glioma (continued). "This study aimed to compare DNA sequencing, IHC, and PCR–RFLP in detecting IDH1 mutations in gliomas." (PMID 33247679, 2020). "IDH1/2 mutations resulting in production of oncometabolite D-2-HG inhibits TETs and many other epigenetic enzymes, but are also highly restricted to gliomas and leukemia." (PMID 33097695, 2020). "Despite their frequency in adults, IDH1 mutations in pediatric glioma are rare, with reports ranging from 0-17% of cases." (PMID 32164789, 2020). "IDH1 mutation has been identified to be one of most important molecular pathological alterations in glioma, but HLA-E showed little association with it." (PMID 32066399, 2020). "The major mutation in glioma is IDH1/IDH2, which is a key metabolic gene in the oxidative decarboxylation of isocitrate in tricarboxylic acid (TCA) cycle, converting isocitrate to ɑ-ketoglutarate as reducing NADP+ to NADPH26." (PMID 31897239, 2020). "On the other hand, IDH1 mutation is highest in grade 4 glioma or GBM that correlates with fast tumor growth and poor survival." (PMID 32616845, 2020). "When considering how the World Health Organization (WHO) Classification of 2016 encourages routine testing for IDH1 mutational status, noninvasive methods of glioma assessment would be highly desirable for patients." (PMID 33121211, 2020). "One major question in the field of glioma with IDH1 mutations is related to the source of 2HG synthesis." (PMID 32575619, 2020). "KM analysis revealed significantly better OS (56.8 vs 22.7 months for IDH1 wild type; log-rank p = 0.01) for glioma patients with IDH1 mutations." (PMID 33552543, 2020). "Mutations in IDH1/2 have been identified in multiple types of human malignancies, such as lower grade glioma, secondary glioblastoma, acute myeloid leukemia, chondrosarcoma, and cholangiocarcinoma." (PMID 32224866, 2020). "In patients with gliomas, intratumour heterogeneity of IDH1 mutations can be considered as a favorable independent prognostic biomarker." (PMID 33228738, 2020). "Patients who have this IDH1 mutation in their glioma have a significantly better prognosis compared to those with IDH1-wildtype lesions of the same histologic grade." (PMID 33302429, 2020). "IDH1 mutations occur in about 20–30% of gliomas and are a promising target for the treatment of cancer." (PMID 33262701, 2020). "Our results demonstrate that a high amount of D-2HG was released into the blood from gliomas with IDH1 mutations." (PMID 32576825, 2020). "By contrast, subtype C3 included more grade II and IDH1-mutated glioma, and was associated with more infiltration of CD4+T cells." (PMID 33425739, 2020). "The most common IDH1 mutation observed in gliomas is the point mutation at position 132 (R132H), which is regarded as a typical IDH1 mutation." (PMID 33102518, 2020). "Despite the fact that ADF cells have not been characterized in terms of possible IDH mutations, the GSH/GSSG ratio measured in this cell line is far from the marked glutathione red/ox unbalance observed for other IDH1 mutated glioma cells." (PMID 32380768, 2020). "To date, in human gliomas, only heterozygotic mutations in IDH-1 and IDH-2 have been reported, with a significant preponderance of IDH-1." (PMID 33212941, 2020). "Providing in vitro or in vivo models with mutated IDH1/2 can help prepare facilities to understand the biology of these mutated genes as glioma markers, as well as help, improve therapeutic strategies." (PMID 33221817, 2020). "This bioinformatics analysis demonstrates the mRNAsi as a reliable index for the IDH1 mutation, histologic grade and OS of glioma and provides a well-applied model for predicting the OS for patients with glioma based on prognostic SRGs." (PMID 32725165, 2020).
glioma (continued). "IDH1/2 mutations represent less aggressive oncogenic mode and independently prove to be a better prognostic factor for survival in glioma patients." (PMID 33552543, 2020). "Oligodendrogliomas are now defined as an infiltrating glioma with the presence of mutation in either IDH1 or IDH2 and co-deletion of chromosomes 1p and 19q, regardless of other histologic features." (PMID 32640746, 2020). "Gliomas with IDH1 mutations are more likely to exhibit homogeneous signal intensity, less contrast enhancement and are more likely to cross the midline to the other hemisphere." (PMID 32582544, 2020). "These gliomas were all wild-type for Idh1, consistent with gliomas in humans in which IDH1 and EGFR mutations tend to be mutually exclusive." (PMID 32727536, 2020). "The fact that patients with IDH1 mutation are more likely to be smokers can provide insight into the role of smoking in glioma formation, as IDH1 mutation is a frequent, likely early event in gliomagenesis." (PMID 32856857, 2020). "The results of Cox proportional hazard regression analysis show that BRAFAMP and IDH1/2WT genotype was an independent predictive factor for glioma with BRAF mutation and BRAFAMP." (PMID 33489866, 2020). "Percentages of samples with IDH1 mutation were 36.1% in grade II glioma, 17.7% in grade III glioma, 14% in grade IV glioma, and 10% in grade I glioma." (PMID 32856857, 2020). "In conclusion, the current study revealed that radiomic features derived from APTW images are associated with IDH1 mutation status in grade II/III gliomas." (PMID 32153362, 2020). "IDH1-mutant glioma grows slower than wild-type glioma and is associated with longer overall survival and progression-free survival and with a better prognosis and survival rate." (PMID 33163535, 2020). "The World Health Organization (WHO) classification of gliomas has been refined and incorporated molecular parameters, namely 1p/19q codeletion, IDH1/2 mutation, and histone H3-K27M, in addition to histology to define many tumor entities." (PMID 31906320, 2020). "The frequency of IDH1 and IDH2 mutations are different in various tumor types: Thus, IDH1 and IDH2 are almost equally frequent in AML, while IDH1 mutations are predominant in gliomas, chondrosarcomas, and cholangiocarcinomas." (PMID 32859092, 2020). "In vitro cultures derived from these tumors either died or led to depletion of the wild-type IDH1 allele, in line with previous reports, suggesting that IDH1mut gliomas require components of the brain microenvironment to maintain their growth." (PMID 33009951, 2020). "Recently, Amankulor and colleagues reported that the IDH1 mutation is associated with a decreased number of immune cells in the glioma tumor microenvironment." (PMID 32392361, 2020). "The biological defects of IDH1 mutations have been investigated predominantly in gliomas and glioblastomas." (PMID 32824685, 2020). "Numerous studies have shown that IDH1 mutations are early molecular changes in diffuse astrocytoma and oligodendroglioma, and approximately 70% of grade II-III glioma and secondary glioblastomas harbor an IDH1 mutation." (PMID 33163535, 2020). "Glioma models carrying the IDH1Mut, in vitro, can be based on the establishment of primary patient cells or generating IDH1 mutated cell lines via gene engineering or editing." (PMID 33221817, 2020). "Isocitrate dehydrogenase (IDH)-1 mutation is an important prognostic factor and a potential therapeutic target in glioma." (PMID 33212941, 2020). "The purpose of this study is to evaluate the potential of quantitative T2-mapping in the detection of IDH1/2 mutation status in grade II-III gliomas." (PMID 31914945, 2020). "We revealed elevation in certain lipids produced along the sphingolipid pathway for IDH1 mutated glioma cells and upregulation of the corresponding enzymes." (PMID 33050528, 2020).
glioma (continued). "Due to the IDH1 mutation, high levels of D2-HG are created that promote the occurrence and development of cancers, such as gliomas and acute myeloid leukemia." (PMID 33262701, 2020). "In this study, the IDH1 mutation in WHO grade III and grade IV glioma-enhanced images was studied, which not only confirms the reliability of radiomics in the study of IDH1 mutations in gliomas of different grades but also broadens its application scope." (PMID 33163535, 2020). "For example, a phase 1 clinical trial is currently ongoing to validate the safety and therapeutic efficacy of an IDH1 R132H mutant peptide vaccine (NOA-16) in newly diagnosed grade III and IV gliomas with an IDH1 mutation (NCT02454634)." (PMID 32291392, 2020). "A cohort of 168 patients with IDH-1 mutated cholangiocarcinoma, chondrosarcoma, and glioma were treated with ivosidenib in order to evaluate pharmacokinetic and pharmacodynamics profiles." (PMID 33182517, 2020). "mTOR inhibitor omipalisib, which potently suppresses both mTORC1 and two activities, showed suppression of cell proliferation in both IDH1 wild type and mutated cells, which indicated that mTOR signaling plays essential roles in both glioma molecular subtypes." (PMID 32224866, 2020). "Recent advances in glioma research indicate that IDH1-mutated cancer exhibits a vulnerability pattern different from that of their wild type counterparts." (PMID 32224866, 2020). "Mutations in IDH1/2 occur in the majority of low grade gliomas and secondary GBM, being less frequent in primary GBM." (PMID 32993063, 2020). "It is clear that the detection of IDH1/2 mutations is necessary to understand glioma pathogenesis and tailor a suitable therapy for patients." (PMID 32856857, 2020). "Since glial tumors have a truly diffusely infiltrating growth pattern within the brain, to date only IDH1/IDH2-mutated glioma cells can be sharply distinguished form reactive glia, using immunostaining." (PMID 32240464, 2020). "The IDH1 R132H variant is predominantly found in gliomas, hematopoietic cancers, carcinoma, and chondrosarcoma." (PMID 32825279, 2020). "Depending on histopathological and transcriptomic features as well as somatic mutation in isocitrate dehydrogenase 1/2 (IDH1/2), the glioma microenvironment can display differences in its immune components." (PMID 33374253, 2020). "Isocitrate dehydrogenase I gene (IDH1) mutations occur in up to 80% of low-grade (WHO grade II) gliomas and about 5% of all glioblastomas (GBM)." (PMID 33101674, 2020). "The characterizations of IDH mutations in the glioma included IDH1 mutation (p.R132H) and IDH2 mutation (p.R172K)." (PMID 32973641, 2020). "Among them, IDH1/2 hotspot mutations have been observed in the vast majority of grade II/III gliomas." (PMID 32171051, 2020). "Although DNA sequencing is regarded as gold standard, IHC seems to be more accurate, easier to perform and cheaper for detecting IDH1/2 mutation in glioma patients." (PMID 32293336, 2020). "Our study also indicates a novel therapeutic strategy for IDH1-mutated gliomas by targeting the small GTPase, Rac1." (PMID 32224866, 2020). "For example, 25 germline SNPs associated with glioma and glioblastoma have been recently tested for their association with the most frequent somatic alterations in these cancer types: IDH1 R132H and 1p/19q deletions." (PMID 32239503, 2020). "In adults, IDH1 mutations are associated with a better prognosis and response to chemotherapy as compared to IDH1/2 wild-type glioma." (PMID 32164789, 2020). "IDH1/2 mutations exist in greater than 70% of lower-grade gliomas (grades II and III) and in some glioblastomas." (PMID 33489866, 2020). "RNA sequencing data identified that Rictor is selectively up-regulated in IDH1-mutated lower grade gliomas." (PMID 32224866, 2020).
glioma (continued). "χ2 and Fisher's exact probability tests were used to determine the significance of associations between MRI features and IDH1 mutation of glioma." (PMID 32582544, 2020). "Other authors have confirmed the existence of three different subgroups among IDHmut gliomas, underlying the key role of other epigenetic modulators apart from mutant IDH1/2, like REST (RE1 Silencing Transcription Factor), in some of these subgroups." (PMID 32570988, 2020). "The 2016 WHO classification generated a combination of the histological and molecular characteristics of glioma, including IDH-1 mutation and 1p/19q codeletion (1p19q co-del)." (PMID 32642801, 2020). "Approximately 80% of low-grade gliomas harbor recurrent mutations in the isocitrate dehydrogenase genes 1 and 2 (commonly referred to as IDH1 and IDH2, respectively)." (PMID 33066121, 2020). "For example, IDH1 gene mutation is highly correlated with glioma survival and is therefore used for glioma classification." (PMID 32616845, 2020). "Based on two hallmarks of glioma, mutation of IDH1 and IDH2 genes, and codeletion of chromosome arms 1p/19q, glioma is primarily distinguished into five principle molecular subtypes." (PMID 33747896, 2020). "Mutation in IDH1 is a stable marker for better prognosis in both lower-grade glioma (LGG) and glioblastoma multiforme (GBM)." (PMID 32003759, 2020). "Consistent with the fact that the mutation of IDH1 and ATRX is associated with prolonged survival in glioma, our result showed that the SNPs in IDH1 and ATRX exerted a higher somatic mutation burden in the low‐risk group than in the high‐risk group." (PMID 32301283, 2020). "Schumacher and colleague demonstrated the promising function of IDH1 mutation–specific vaccination for glioma treatment." (PMID 33228738, 2020). "Levels of 2-HG were found to be significantly higher in IDH1-mutant glioma and acute myeloid leukemia cell lines than wild-type, causing epigenetic dysfunction and inducing a DNA hypermethylation phenotype." (PMID 33182517, 2020). "IDH1 is one important glioma biomarker and IDH1 mutation along with 1p/19q is a part of the molecular diagnosis in the updated 2016 WHO classification." (PMID 33014836, 2020). "Glioma cases were analyzed for IDH1/2 mutations and MGMT promoter methylation by DNA sequencing and methylation-specific PCR, respectively." (PMID 33552543, 2020). "In patients with glioma, IDH1 mutation has been shown to be an independent positive prognostic biomarker with improved progression-free survival and treatment outcome in comparison to the IDH1 wildtype." (PMID 33121211, 2020). "IDH1 mutations have been identified in many types of cancers including glioma, hepatoma, leukemia, colon cancer and prostate cancer." (PMID 32373065, 2020). "In conclusion, this bioinformatics study demonstrates the mRNAsi as a reliable index for the IDH1 mutation, histologic grade and OS of glioma patients and provides a well-applied model for predicting the OS for patients with glioma based on prognostic SRGs." (PMID 32725165, 2020). "For instance, IDH1/2-mutated gliomas harbor a characteristic methylation pattern defined as the glioma-CGI methylator phenotype and associate with favorable prognosis." (PMID 32999376, 2020). "The 2016 WHO Classification of Tumors of the Central Nervous System5 recommends using IDH1/2 mutation and 1p/19q co-deletion (codel) status in combination with histology to classify infiltrating gliomas." (PMID 33244057, 2020). "Downregulation of PDPN has been observed in glioma carrying IDH1 mutations, which can increase chances for survival in patients carrying IDH1Mut38." (PMID 33221817, 2020).